RN7SL525P (RNA, 7SL, cytoplasmic 525, pseudogene)
Gene: Miscellaneous RNA gene on chromosome 19 (58,543,299 to 58,543,578, reverse strand). Ensembl gene ENSG00000264910.
Homologues: Orthologues: chimpanzee Metazoa_SRP (98% identical), macaque Metazoa_SRP (90% identical). Paralogues in human: Metazoa_SRP (83% identical), Metazoa_SRP (82% identical), RN7SL602P (82% identical), RN7SL718P (82% identical), Metazoa_SRP (81% identical), RN7SL121P (80% identical), RN7SL387P (80% identical), Metazoa_SRP (80% identical), RN7SL524P (79% identical), RN7SL353P (78% identical), RN7SL440P (78% identical), Metazoa_SRP (77% identical), and 714 more.